CHST7 (carbohydrate sulfotransferase 7)
Description:
Sulfotransferase that utilizes 3'-phospho-5'-adenylyl sulfate (PAPS) as sulfonate donor to catalyze the transfer of sulfate to position 6 of non-reducing N-acetylglucosamine (GlcNAc) residues. Preferentially acts on mannose-linked GlcNAc. Also able to catalyze the transfer of sulfate to position 6 of the N-acetylgalactosamine (GalNAc) residue of chondroitin. Also acts on core 2 mucin-type oligosaccharide and N-acetyllactosamine oligomer with a lower efficiency. Has weak or no activity toward keratan sulfate and oligosaccharides containing the Galbeta1-4GlcNAc. Catalyzes 6-O-sulfation of beta-benzyl GlcNAc but not alpha- or beta-benzyl GalNAc.
Synonyms: C6ST-2; GST-5; C6ST2
Tractability: Antibody: UniProt predicts a signal peptide or a membrane-spanning region. PROTAC: ubiquitination databases record sites on it.
Gene: Protein-coding gene on chromosome X (46,573,391 to 46,598,496, forward strand). Ensembl gene ENSG00000147119.
Subcellular location: Golgi apparatus membrane
Subcellular location (Human Protein Atlas): Nucleoplasm; Vesicles
Pathways (Reactome):
Metabolism: CS-GAG biosynthesis
Gene Ontology:
Molecular function: chondroitin 6-sulfotransferase activity; N-acetylglucosamine 6-O-sulfotransferase activity; sulfotransferase activity
Biological process: chondroitin sulfate proteoglycan biosynthetic process; N-acetylglucosamine metabolic process; sulfur compound metabolic process; polysaccharide metabolic process; carbohydrate metabolic process
Cellular component: Golgi membrane; membrane; Golgi apparatus
Homologues: Orthologues: chimpanzee CHST7 (99% identical), macaque CHST7 (98% identical), rabbit CHST7 (95% identical), pig CHST7 (94% identical), guinea pig CHST7 (91% identical), mouse Chst7 (87% identical), rat Chst7 (87% identical), tropical clawed frog chst7 (51% identical), zebrafish chst7 (46% identical), Drosophila melanogaster CG31637 (20% identical), Drosophila melanogaster CG9550 (13% identical). Paralogues in human: CHST2 (42% identical), CHST6 (29% identical), CHST5 (29% identical), CHST4 (27% identical), CHST1 (25% identical), CHST3 (23% identical).
Diseases named in the same sentence as CHST7 in open-access papers:
CHST7 is named in the same sentence as 15 diseases in open-access papers, as found by Europe PMC text mining. Sharing a sentence is not in itself a finding about the gene and the disease. The quoted sentences say what the papers report.
colorectal cancer (3 papers, 2021 to 2023). A primary or metastatic malignant neoplasm that affects the colon or rectum. "The results indicate that CHST7 gene hypermethylation in the white blood cells is associated with the increased risk of colorectal cancer (N = 432, OR = 4.45, P < 0.001)." (PMID 37545696, 2023). "On the other hand, CHST7 expression is NSCLC candidate biomarker, while CHST7 gene hypermethylation in white blood cells is associated with increased risk of colorectal cancer." (PMID 37545696, 2023). "A similar result was obtained in the evaluation of CHST7 role in colorectal cancer." (PMID 37545696, 2023).
adenoma (2 papers, 2022 to 2023). A neoplasm arising from the epithelium. "In this study, we found that CHST7 hypermethylation in PAs was associated with the tumor proliferation and cell differentiation of SF-1-lineage adenomas, and CHST7 hypomethylation was related to the cell differentiation of the Pit-1 and T-PIT lineages." (PMID 35954244, 2022). "CHST7 is a novel pituitary gland specific protein in SF-1 lineage adenomas with a potential role in gonadotroph cell proliferation and lineage differentiation in PA." (PMID 38023219, 2023). "The RT-PCR and IHC experiments also showed that there were more patients with low CHST7 with SF-1-lineage adenomas and more patients with high CHST7 with a Pit-1 lineage." (PMID 35954244, 2022). "In summary, CHST7 is a novel pituitary gland specific protein in SF-1 lineage adenomas with a potential role in gonadotroph cell proliferation and lineage differentiation in PAs." (PMID 35954244, 2022).
gastric cancer (2 papers, 2022). A primary or metastatic malignant neoplasm involving the stomach. "In the current study, we firstly revealed the expression pattern and functions of CHST7 in oxaliplatin resistance of gastric cancer." (PMID 35802620, 2022). "Glycosaminoglycan biosynthesis-chondroitin sulfate metabolic pathway genes were positively or negatively correlated with oncogenes and tumor suppressor genes of gastric cancer, respectively, whereas high expression of CHST7 was positively correlated with that of four significantly upregulated genes." (PMID 35326589, 2022).
acute lymphoblastic leukemia (1 paper, 2021). Leukemia with an acute onset, characterized by the presence of lymphoblasts in the bone marrow and the peripheral blood. "CHST2 and CHST7 were used as biomarkers for pediatric high-risk B-precursor acute lymphoblastic leukemia, and patients with high CHST2 and CHST7 expression had poor 4-year relapse-free survival rates." (PMID 34288811, 2021).
gonadotroph adenoma (1 paper, 2022). "In the SF-1 lineage, the ROC value of CHST7 was better than that of either ESR1 or SF-1, which were adopted as classification indices for gonadotroph adenoma in the 2017 WHO classification." (PMID 35954244, 2022).
non-small cell lung carcinoma (1 paper, 2023). A group of at least three distinct histological types of lung cancer, including non-small cell squamous cell carcinoma, adenocarcinoma, and large cell carcinoma. "In this regard, possible application of the serum CHST7 concentration in differentiation of non-malignant pulmonary inflammations and non-small cell lung carcinoma (NSCLC) has been shown (N = 125, AUC = 0.85, sensitivity = 78%, specificity = 75%)." (PMID 37545696, 2023).
cancer (3 papers, 2022 to 2024). A tumor composed of atypical neoplastic, often pleomorphic cells that invade other tissues. "High expression of CHST7 was associated with a poor prognosis (p = 0.0079) and, thus, its protein may be a promising drug target for treating high-matrisome cancer types." (PMID 35326589, 2022). "Sulfotransferase activity, including that of CHST7, plays a key role in the transformation to an aggressive tumor type in cancer." (PMID 35326589, 2022). "Carbohydrate sulfotransferases, such as CHST7, CHST11-13, or CHST15, have been suggested to be relevant in developing and progressing multiple types of cancer, as in PDA." (PMID 39098880, 2024).
tumor (3 papers, 2021 to 2022). "We then analyzed the relationship of the CHST7 expression profile with PA tumor proliferation, invasion, and differentiation." (PMID 35954244, 2022). "At the cellular level, USP18, TLR7, IL21R, GCNT1 and CHST7 were expressed in various tumor cell lines, while the expression of LHX2, IL2RA and IL5RA was low in CCLE." (PMID 34001679, 2021). "We found a positive correlation between the mRNA levels of CHST7, Pit-1, and SSTR2, which suggests that CHST7 may function at the crossroads of tumor cell differentiation." (PMID 35954244, 2022). "We speculated that CHST7 inhibited tumor proliferation but not cavernous sinus invasion based on the RT-PCR experiments." (PMID 35954244, 2022).
CHST7 also shares sentences with these, for which no sentence is quoted: glioma (2 papers); autism (1); colon adenocarcinoma (1); lung carcinoma (1); myeloma (1); Pituitary Adenomas (1); rectum adenocarcinoma (1).